NUAK1 (NUAK family kinase 1)
Diseases named in the same sentence as NUAK1 in open-access papers (continued):
Sharing a sentence is not in itself a finding about the gene and the disease.
cancer (continued). "The phosphorylation of MYPT at S445 by NUAK1 increases the activity of GSK3β for NRF2 and suppresses the cellular ROS response thereby reducing the capacity of cancer cells to maintain adaptation to high ROS production." (PMID 38434478, 2024). "We also observed the early effect of NUAK1 on the Akt Ser-473 phosphorylation in the U87 and SW480 cancer cell lines." (PMID 38135881, 2023). "Therefore, we explored whether NUAK1 regulates senescence or cancer cell survival." (PMID 38135881, 2023). "NUAK1 was required for the Akt/FOXO1/3a axis, regulating p21CIP1, p27KIP1, and FoxM1 expression and cancer cell survival upon EGFR stimulation." (PMID 38135881, 2023). "Analysis of human tissue data revealed that NUAK1 expression positively correlates with EGFR expression and Akt Ser-473 phosphorylation in several human cancers." (PMID 38135881, 2023). "NUAK1 and NUAK2 are AMPK (AMP-activated Protein Kinase) related kinases with diverse functions in cancer cells." (PMID 36295658, 2022). "Despite the limited number of studies that experimentally elucidate the role of NUAK1 and NUAK2 in cancer development, both kinases have been found amplified in different tumors." (PMID 34685740, 2021). "However, NUAK1 could also promote cancer cell survival under glucose deprivation." (PMID 32754444, 2020). "Our findings demonstrate a synergistic anticancer effect in response to combined treatment with NUAK1 inhibitor (WZ4003) and ULK1 inhibitor (SBI-0206965) in different types of cancer cells." (PMID 32873786, 2020). "NUAK2 and NUAK1 share roughly 60% sequence identity, and have shared functions in cytoskeletal remodeling, metabolic adaption, proliferation, and EMT—key hallmarks of cancer." (PMID 40770117, 2025). "Together, the data suggest that modulation of NUAK2 expression does not affect NUAK1, which is consistent with previous reports in other cancers." (PMID 40770117, 2025). "Whether NUAK2 is also relevant for the regulation of Akt phosphorylation is unknown, but it would be essential to address it because NUAK1 and NUAK2 are differentially expressed in normal and cancer tissues." (PMID 38135881, 2023). "Consistently, depletion of NOTCH3, NUAK1, or PDPK1 decreased cancer cell migration." (PMID 36072578, 2022). "Initially, NUAK1 and NUAK2 were described in brain tissue, however, further research has demonstrated their role in cell migration and polarization, as well as invasive and metastatic processes in cancer cells." (PMID 34685740, 2021). "In our study, we sought to determine whether selectively inhibiting NUAK1 and ULK1 could be an effective way to target oxidative stress homeostasis in cancer cells." (PMID 32873786, 2020). "For instance, NUAK1 has been shown to play key roles in cancer cell survival during energetic or oxidative stress, while NUAK2 is frequently amplified in a spectrum of human cancers and both participate in facilitating cell motility required for cancer cell dissemination and metastasis." (PMID 38939918, 2024). "However, the suitability of NUAK1 as a potential therapeutic target in PDAC, or other cancers, must ultimately be weighed against the potential toxicity arising from the herein‐described requirement for NUAK1 to maintain genomic integrity through control of centrosome replication." (PMID 36975767, 2023). "In this review, we aim to unravel the role of NUAK1 and NUAK2 as members of the AMPK-related kinase family of proteins and to examine their various cellular functions, with a focus on the implications of altered expression and the potential subsequent modified activities in different cancer types." (PMID 34685740, 2021). "Therefore, we predict that dual inhibition of NUAK1 and ULK1 could induce a significant synergistic cytotoxic effect on various cancer types." (PMID 32873786, 2020).
cancer (continued). "In addition, miR-204-5p serves as a cancer suppressor gene by modulating oncogenic Wnt/FZD signaling pathways, inhibiting NUAK family kinase 1 (NUAK1) in NSCLC, and mediating a long-noncoding RNA (lncRNA) MALAT1 effect on the epithelial-to-mesenchymal transition (EMT) and cells invasion." (PMID 32102656, 2020). "Thus, NUAK1 might cross-talk to impact TGF β-mediated EMT in EOC spheroids, as observed in other cancer cell systems; this will be a focus of on-going study by our group." (PMID 32429240, 2020). "The spectrum of actions of NUAK1 and NUAK2 may range from the control of gene expression to the regulation of the cell cycle and cell differentiation, important cellular properties that define adult tissue homeostasis and diseases, such as tissue fibrosis and cancer." (PMID 30622137, 2019). "Here we demonstrate that NUAK1, like AMPK, is active in cancer cells in the absence of LKB1." (PMID 29106388, 2018).
neurodegenerative disease (3 papers, 2022 to 2025). A disorder of the central nervous system characterized by gradual and progressive loss of neural tissue and neurologic function. "NUAK1 has also been implicated in tau phosphorylation and stabilization leading to interest in this kinase as a therapeutic target for neurodegenerative disease." (PMID 41257021, 2025). "The deregulation of NUAK1 activity, usuallyinvolving overexpressionof endogenous protein levels, in both cancer and in neurodevelopmentaldisorders and neurodegenerative disease has encouraged the developmentof inhibitors for this kinase." (PMID 39967649, 2025).
neurodevelopmental disorder (2 papers, 2018 to 2024). A behavioral and cognitive disorder with onset during the developmental period that involves impaired or aberrant development of intellectual, motor, or social functions. "Here the authors report behavioral and cortical development in mice heterozygous for Nuak1, suggesting loss of function mutations in one copy of Nuak1 may contribute to neurodevelopmental disorders." (PMID 30327473, 2018). "Overall, our results indicate that Nuak1 is haploinsufficient regarding its role in the development of cortical connectivity and support the hypothesis that loss-of-function mutations in Nuak1 participates in the etiology of neurodevelopmental disorders." (PMID 30327473, 2018). "In order to investigate the effect of Nuak1 haploinsufficiency on mouse behavior, we generated age-matched cohorts of WT and NUAK1+/− mice and performed a battery of behavioral assays relevant to neurodevelopmental disorders." (PMID 30327473, 2018).
NUAK1 also shares sentences with these, for which no sentence is quoted: intrahepatic cholangiocarcinoma (4 papers); lymphoma (3); glioblastoma (2); Intellectual disability (2); schizophrenia (2); T cell lymphoma (2); attention deficit-hyperactivity disorder (1); cervical squamous cell carcinoma (1); COVID-19 (1); endometrial squamous cell carcinoma (1); esophageal adenocarcinoma (1); esophageal squamous cell carcinoma (1); fibrosis (1); glaucoma (1); head and neck cancer (1); leukemia (1); liver neoplasm (1); lung adenocarcinoma (1); lung squamous cell carcinoma (1); medulloblastoma (1); metastatic cancer (1); ovarian tumours (1); prostate adenocarcinoma (1); prostate tumor (1); renal cell carcinoma (1); squamous cell carcinoma (1).